CD6 (CD6 molecule)
Diseases named in the same sentence as CD6 in open-access papers (continued):
Sharing a sentence is not in itself a finding about the gene and the disease.
migraine (2 papers, 2024 to 2025). "Further studies are needed to elucidate the precise mechanisms underlying this association and to explore the potential of CD6 as a therapeutic target for migraines." (PMID 39170074, 2024). "Nine proteins—including CD6 and beta-NGF—were positively associated with migraine, while others like CCL19 showed inverse correlations." (PMID 40426647, 2025). "In the context of migraines, it is hypothesized that elevated levels of CD6 could potentially enhance T cell activation and proliferation, contributing to the neurogenic inflammation characteristic of migraines." (PMID 39170074, 2024). "The alterations in TRAIL and CD6 levels could be one of the mechanisms through which obesity influences migraine pathogenesis." (PMID 39170074, 2024). "However, it’s important to note that the relationship between CD6 levels and migraines is likely to be complex and multifactorial." (PMID 39170074, 2024). "The analysis of T-cell surface glycoprotein CD6 isoform levels (PH4 = 0.614) and CD8 expression on terminally differentiated CD8+ T cells (PH4 = 0.533) provided moderate evidence in support of the colocalization analysis in the context of migraine." (PMID 39170074, 2024).
non-small cell lung carcinoma (2 papers, 2024 to 2025). A group of at least three distinct histological types of lung cancer, including non-small cell squamous cell carcinoma, adenocarcinoma, and large cell carcinoma. "For example, Cd6 is a lymphocyte surface marker involved in TCR signaling in non-small cell lung cancer and has three isoforms." (PMID 39346085, 2024).
Obesity (2 papers, 2024 to 2025). Accumulation of substantial excess body fat. "Alterations in CD6 levels in obesity could potentially lead to dysregulated immune responses, thereby contributing to the chronic inflammation associated with obesity." (PMID 39170074, 2024). "The study reported associations between smoking, obesity, and altered expression of inflammatory markers such as IL-1α, CDCP1, TRAIL, and CD6." (PMID 40426647, 2025). "Moreover, in the study, obesity was associated with altered levels of TNF-related apoptosis-inducing ligand (TRAIL) and T-cell surface glycoprotein CD6 isoform, aligning closely with findings from prior research." (PMID 39170074, 2024).
ovarian carcinoma (2 papers, 2022 to 2025). A malignant neoplasm originating from the surface ovarian epithelium. "Our study suggested that CD6 was N-glycosylated in ovarian cancer cells with two N-glycosylation sites at Asn345 and Asn348." (PMID 36482940, 2022). "CD6, CXCL9, and CXCL13 were associated with favorable outcomes in BRCA1-mutant ovarian cancers." (PMID 40647506, 2025).
T cell lymphoma (2 papers, 2024 to 2025). "recently confirmed that CD6 is indeed highly expressed on most T cell lymphoma cell lines." (PMID 39840036, 2024). "Importantly, a CD6-targeted antibody-drug conjugate (anti-CD6-ADC) selectively kills T cell lymphoma cells in vitro and reverses the development of tumors in vivo in mouse models of T cell lymphoma (TCL)." (PMID 39840036, 2024).
type 2 diabetes (2 papers, 2021 to 2023). "Studies in animal models have found that certain types of T cells, such as CD6+ and CD4+, are moderately increased in patients with type 2 diabetes and are linked with proteinuria." (PMID 37554330, 2023). "Although there is evidence of stenosis if T cells are engaged in the development of DN, limited animal experiments have found that CD6+ and CD4 + T cells are moderately increased in type 2 diabetes patients and are correlated with proteinuria." (PMID 34424825, 2021).
acute graft versus host disease (1 paper, 2024). A syndrome of immunologically mediated tissue damage that may occur following an allogeneic transplant, usually affecting the skin, liver, and GI tract. "recently examined expression of CD6 in patients after allogeneic cell transplantation and found that CD6 expression was reduced in Treg and CD8+T cells in acute graft-versus-host disease (aGvHD) compared to healthy donors." (PMID 39840036, 2024).
acute leukemia (1 paper, 2017). A clonal (malignant) hematopoietic disorder with an acute onset, affecting the bone marrow and the peripheral blood. "Unmanipulated bone marrow followed by CD6-depleted mobilized blood cells produced long-term remissions in advanced cases of acute leukemia; CD6-depleted PBSC provides NK cells, stem cells, and a minority of suppressive CD8-positive cells." (PMID 28638379, 2017).
acute lymphoblastic leukemia (1 paper, 2021). Leukemia with an acute onset, characterized by the presence of lymphoblasts in the bone marrow and the peripheral blood. "For example, the CD6 gene is overexpressed in a subset of leukemias, with expression of over 100 transcripts per million (TPM) in 10% of acute myeloid leukemia (AML), 18% of T-lineage acute lymphoblastic leukemia (T-ALL), and 2% of B-ALL, but virtually no expression in other cancerous tissues." (PMID 34789196, 2021).
alcoholic liver damage (1 paper, 2022). "Genetically predicted CD6 was associated with alcoholic liver damage and degeneration of intervertebral disc (musculoskeletal system), which were considered deleterious." (PMID 36253349, 2022).
ankylosing spondylitis (1 paper, 2022). An autoimmune chronic inflammatory disorder characterized by inflammation in the vertebral joints of the spine and sacroiliac joints. "The CD6 rs17824933G allele was further associated with lower risk of ankylosing spondylitis in the whole IBD cohort." (PMID 36211446, 2022). "Logistic regression analysis of CD6 SNP association with CD prognosis (top), UC extent (middle), and ankylosing spondylitis in IBD patients (bottom), corrected for sex and smoking." (PMID 36211446, 2022). "Regarding the appearance of extra-intestinal manifestations, logistic regression analyses showed a significant association of homo- or heterozygous combinations of the CD6 rs17824933G allele with lower risk of ankylosing spondylitis in the whole cohort of IBD patients." (PMID 36211446, 2022). "Regarding CD6, association was observed with CD ileal location (rs17824933G) and poor prognosis (rs12360861G), and with left-sided or extensive UC, and absence of ankylosing spondylitis in IBD (rs17824933G)." (PMID 36211446, 2022).
bacteremia (1 paper, 2025). "Martínez‐Florensa's research indicates that CD6.PD3 initiates a reduction in serum concentrations of pro‐inflammatory cytokines as well as bacteremia." (PMID 40453734, 2025).
bronchitis (1 paper, 2018). An acute or chronic inflammatory process affecting the bronchi. "Infant CD2 suffered from pharyngitis; CD3 suffered from an upper respiratory tract infection; CD5 suffered from otitis; CD6 and CD8 suffered from an upper respiratory tract infection and also from otitis, and control C5 suffered from bronchitis." (PMID 29458413, 2018).
chronic hepatitis B (1 paper, 2022). "Our data showed that patients with AIH exhibited significantly higher expression of CD6 in the liver as compared to primary biliary cholangitis (PBC), chronic hepatitis B (CHB), non-alcoholic liver disease (NAFLD), and healthy controls (HC)." (PMID 36159854, 2022).
co-infection (1 paper, 2025). "In parallel, ADGRE5-ALCAM-related co-stimulatory and adhesion interactions showed pair-specific dynamics: CD6-ALCAM and ITGAV-ITGB1-ADGRE5 were most prominent in the HIV-mono group and diminished with Mtb co-infection, whereas CD55-ADGRE5 did not display a comparable monotonic trend." (PMID 41394852, 2025).
colon cancer (1 paper, 2025). "The design of CAR-T cells with CD6 as a chimeric receptor has shown cytotoxic effects on ALCAM+ but not CD318+ human colon cancer cell lines." (PMID 40391211, 2025).
encephalitis (1 paper, 2025). An acute inflammatory process affecting the brain parenchyma. "Similar to C57BL/6 mice, both WT and CD6 KO mice on the DBA background exhibited only mild clinical symptoms of encephalitis with 100% survival rate out to day 28 PI." (PMID 39679790, 2025).
endotoxemia (1 paper, 2013). "Mice injected intraperitoneally with recombinant CD6 were protected from lethality due to endotoxemia and presented a reduction in serum TNFα abundance." (PMID 24236088, 2013).
epilepsy (1 paper, 2025). A brain disorder characterized by episodes of abnormally increased neuronal discharge resulting in transient episodes of sensory or motor neurological dysfunction, or psychic dysfunction. "In the pilocarpine-induced rat model of epilepsy, the downregulation of the TLR4/NF-kB inflammatory pathway in epilepsy inhibited microglial activation and the expression of the inflammatory factor CD6, which reflects the strong phagocytic ability of microglia." (PMID 39851521, 2025).
fungal infection (1 paper, 2022). "CD5 has a protective role against fungal infection by recognizing and binding to fungal species via β-glucan, while CD6 recognizes and binds to bacterial LPS." (PMID 34983375, 2022).
glomerulonephritis (1 paper, 2022). A renal disorder characterized by damage in the glomeruli. "CD6 blockade ameliorates acute immune complex–mediated glomerulonephritis." (PMID 34981775, 2022).
gout (1 paper, 2023). A condition characterized by painful swelling of the joints, which is caused by deposition of urate crystals. "Six significantly distinct proteins were identified in the serum proteomic profile of gout flares, these patients having elevated circulating concentrations of MMP-1, IL-6, VEGFA, and CCL23 and decreased DNER (Delta and Notch-like epidermal growth factor-related receptor) and CD6 levels." (PMID 37810213, 2023).
Granuloma (1 paper, 2025). A compact, organized collection of mature mononuclear phagocytes, which may be but is not necessarily accompanied by accessory features such as necrosis. "Interestingly, TNF, WNT, CD6, APRIL, EPHA, and SEMA6 signaling pathways were reduced in Mtb granulomas compared to MAH granulomas." (PMID 41586350, 2025).
Graves disease (1 paper, 2023). Graves' disease is an autoimmune disorder that leads to overactivity of the thyroid gland (hyperthyroidism).It is caused by an abnormal immune system response that causes the thyroid gland to produce too much thyroid hormones. "Previous studies have indicated that miR-4442, which targets CD6, may be involved in Grave’s disease and Hashimoto’s thyroiditis and in the proliferation or apoptosis in small airway epithelial cells exposed to transforming growth factor-β." (PMID 37510319, 2023).
heart failure (1 paper, 2024). Inability of the heart to pump blood at an adequate rate to meet tissue metabolic requirements. "We discovered that 7 out of these 91 inflammatory factors influence heart failure, with 4 showing a significant causal relationship (CXCL9, IFN-γ, LIFR, UPA) and 3 being potentially related influencing factors (DNER, MMP-1, CD6)." (PMID 39726944, 2024). "Here, DNER is a potential protective factor against heart failure, while MMP-1 and CD6 are potential risk factors." (PMID 39726944, 2024). "Three inflammatory factors had a potential causal relationship with heart failure, with DNER as a potential protective factor, and MMP-1 and CD6 as potential promotive factors." (PMID 39726944, 2024).
helminth infection (1 paper, 2018). "In summary, our results expand the pathogen binding properties of CD5 and CD6 and suggest their therapeutic potential against helminth infections." (PMID 30500820, 2018). "PECs harbor CD5 and/or CD6 expressing immune cells involved in helminth infection protection." (PMID 30500820, 2018).
Hepatitis (1 paper, 2022). Inflammation of the liver. "The spatial proximity between CD6+CD4+ T cells and ALCAM+ hepatocytes is observed in the interface hepatitis lesion." (PMID 36159854, 2022).
inflammatory skin disease (1 paper, 2022). Inflammatory skin disorders covers a broad category that includes many conditions ranging in severity, from mild itching to grave medical health complications These disorders are common in people of all ages and races. "This may at least in part explain the divergent effects observed when treating inflammatory skin diseases with antibodies to CD6 versus CD2." (PMID 36353616, 2022). "Importantly, given the lack of CD86 and CD80 expression in KCs, our study indicates new therapeutic options for inflammatory skin diseases, targeting CD6 directly in the skin rather than using systemic routes." (PMID 36353616, 2022). "Moreover, our findings may provide a molecular basis for selective interference with either CD6/CD166/CD318, or CD2/CD58, or both to specifically treat different types of inflammatory skin diseases." (PMID 36353616, 2022).
leukopenia (1 paper, 2022). "The CD6 rs17824933G allele was associated with decreased risk of neutropenia, and the CD6 rs11230563T allele with increased leukopenia and neutropenia, but decreased ESSDAI peripheral nervous system (PNS) activity." (PMID 35372412, 2022).
lymphopenia (1 paper, 2021). Reduction in the number of lymphocytes. "Since Themis–/– mice have a higher proportion of CD44hi cells due to lymphopenia, we gated on CD44lo cells for our analysis of CD5, CD6 and CD44 expression." (PMID 33897691, 2021).
Mycobacterium infection (1 paper, 2021). Infections with bacteria of the genus Mycobacterium. "The role of the remaining 7 genes (CD2, CD6, CD247, ZAP70, CD3D, SH2D1A, and CD3E) in T-cell signaling and modulation of host immune responses in mycobacterium infections is also supported." (PMID 35198572, 2021).
Opportunistic infection (1 paper, 2023). An infection that is caused by a pathogen that would generally not be able to cause an infection in a host with a normal immune system. "If these patients are still under the treatment of the CD6-ADC, their pathogen-specific T cells will also be sensitive to the CD6-ADC–mediated killing, which could lead to opportunistic infections." (PMID 37917882, 2023).
respiratory infections (1 paper, 2025). "The additional diagnosis codes from CD4 to CD6 were excluded since these episodes could likely be due to other causes than respiratory infections and including them in the case definition might cause noise to the surveillance." (PMID 40843520, 2025).
rosacea (1 paper, 2025). A chronic erythematous skin disorder that affects the face. "Furthermore, CXCL11 levels and T-cell surface glycoprotein CD6 isoform levels are risk factors for rosacea, while MCP-1 levels and PD-L1 levels are protective factors for rosacea." (PMID 41431076, 2025).
sarcopenia (1 paper, 2024). Progressive decline in muscle mass due to aging which results in decreased functional capacity of muscles. "Several inflammatory cytokines, such as CD6, HGF, and IL-7, have demonstrated suggestive associations with sarcopenia-related traits." (PMID 39193020, 2024).
scoliosis (1 paper, 2024). A congenital or acquired spinal deformity characterized by lateral curvature of the spine. "In addition, scoliosis was causally related to 4 common IFs, including T-cell surface glycoprotein CD6 isoform, hepatocyte growth factor, interleukin-18, and tumor necrosis factor ligand superfamily members." (PMID 38875409, 2024).
Splenomegaly (1 paper, 2017). Abnormal increased size of the spleen. "Further assessment of the underlying causes of lower splenomegaly found in CD6−/− mice undergoing cGvHD was carried out by analyzing in vivo the levels of both proliferating and apoptotic spleen cells." (PMID 28611770, 2017). "The assessment of splenomegaly at the end of the follow-up period (week 5) showed, however, statistically significant lower total spleen cell numbers (left) and spleen weight (right) in CD6−/− mice compared with their CD6+/+ counterparts." (PMID 28611770, 2017).
spondylolisthesis (1 paper, 2024). A condition in which there is forward displacement of a vertebral bone over the on below it. "However, there are few reports related to the involvement of CD6/CD6 isoform in bone homeostasis as well as SDDs, and we found that genetically predicted CD6 isoform promotes the onset of spondylolisthesis/spondylolysis." (PMID 38895179, 2024). "Spondylolisthesis/spondylolysis also had no causal effect on the levels of STAMBP (p = 0.5197), CD6 isoform (p = 0.7240), MCP2 (p = 0.5843), and LAP‐TGF‐β1 (p = 0.0879)." (PMID 38895179, 2024). "In the MR analysis of PD/SD on TNF‐β, spondylolisthesis/spondylolysis on STAMBP and CD6 isoform, although the Cochran's Q p‐value for IVW <0.05 indicated the presence of heterogeneity, the heterogeneity was considered acceptable in this study using random effects IVW." (PMID 38895179, 2024).
Stroke (1 paper, 2022). Sudden impairment of blood flow to a part of the brain due to occlusion or rupture of an artery to the brain. "In addition, we have identified CD6, a lymphocyte surface receptor, associated with an increased risk of any stroke." (PMID 36253349, 2022). "The association of the genetic variants selected as instrumental variables for four proteins (TFPI, TMPRSS5, CD40 and CD6) colocalized with the stroke associations (posterior probability (PP) ≥0.7) i.e. the associations in these regions were likely due to the same underlying causal variants." (PMID 36253349, 2022). "Notably, we found for TFPI, CD40 and CD6 that >80% of the posterior probability of colocalization of the primary genetic association with stroke and the respective protein levels were explained by a single variant (rs67492154, rs4810485 and rs2074227 for TFPI, CD40 and CD6, respectively)." (PMID 36253349, 2022). "The genetic associations with stroke colocalize (Posterior Probability >0.7) with the genetic associations of four proteins (TFPI, TMPRSS5, CD6, CD40)." (PMID 36253349, 2022). "We, therefore, focused further analyses on the proteins with cis-pQTLs only (i.e. TFPI, TMPRSS5, CD40, MMP12, IL6RA, CD6), as these associations with stroke are unlikely to be due to pleiotropy." (PMID 36253349, 2022).
thalassemia (1 paper, 2022). An inherited blood disorder characterized by a decreased synthesis of one of the polypeptide chains that form hemoglobin. "We characterized the thalassemia phenotypes of the HUDEP-2 beta-thal clones with PPEs (CD6, CD17, CD19, IVS-I-1, IVS-I-5, CD39, CD71/72, IVS-II-1, and IVS-II-745) and IPEs (-88 and CD26)." (PMID 35563395, 2022).
vasculitis (1 paper, 2023). "Mice treated with the CD6-ADC showed significantly attenuated disease with only mild vasculitis and a few focal lesions." (PMID 37917882, 2023).